ATAD2 (ATPase family AAA domain containing 2)
Description:
May be a transcriptional coactivator of the nuclear receptor ESR1 required to induce the expression of a subset of estradiol target genes, such as CCND1, MYC and E2F1. May play a role in the recruitment or occupancy of CREBBP at some ESR1 target gene promoters. May be required for histone hyperacetylation. Involved in the estrogen-induced cell proliferation and cell cycle progression of breast cancer cells.
Synonyms: ANCCA; PRO2000; DKFZp667N1320; MGC5254; MGC29843; CT137
Tractability: Small molecule: a structure with a bound ligand is known; a high-quality ligand is known. PROTAC: UniProt records ubiquitination sites on it; ubiquitination databases record sites on it; its protein half-life has been measured; a small molecule that binds it is known.
Target class: Epigenetic regulator; Bromodomain; Reader
Chemical probes: BAY-850 (high quality), CHEMBL3590405, GSK8814 (high quality)
Gene: Protein-coding gene on chromosome 8 (123,319,850 to 123,416,350, reverse strand). Ensembl gene ENSG00000156802.
Subcellular location: Nucleus
Subcellular location (Human Protein Atlas): Nucleoplasm
Pathways (Reactome):
Gene expression (Transcription): TFAP2 (AP-2) family regulates transcription of growth factors and their receptors
Gene Ontology:
Molecular function: ATP hydrolysis activity; protein binding; chromatin binding; ATP binding
Biological process: positive regulation of DNA-templated transcription; nucleosome assembly; nucleosome disassembly; transcription initiation-coupled chromatin remodeling
Cellular component: extracellular exosome; nucleoplasm; nucleus
Genetic constraint (gnomAD): Loss-of-function variants: 43 observed, 123.59 expected, observed/expected ratio (o/e) 0.35, 90% interval 0.27 to 0.45. The upper end of that interval is the gene's LOEUF score, 0.45, which puts it in group 1 of 6, group 1 being the genes least tolerant of losing a copy. Missense variants: 1,206 observed, 1,475 expected, observed/expected ratio (o/e) 0.82, 90% interval 0.78 to 0.86. Synonymous variants: 544 observed, 516.46 expected, observed/expected ratio (o/e) 1.05, 90% interval 0.98 to 1.13.
Homologues: Orthologues: chimpanzee ATAD2 (99% identical), macaque ATAD2 (97% identical), pig ATAD2 (92% identical), dog ATAD2 (91% identical), mouse Atad2 (65% identical), zebrafish atad2 (53% identical), Caenorhabditis elegans lex-1 (30% identical). Paralogues in human: ATAD2B (50% identical).
Diseases named in the same sentence as ATAD2 in open-access papers:
ATAD2 is named in the same sentence as 64 diseases in open-access papers, as found by Europe PMC text mining. Sharing a sentence is not in itself a finding about the gene and the disease. The quoted sentences say what the papers report.
breast carcinoma (31 papers, 2013 to 2026). "The high ATAD2 expression in breast cancer (BC) is caused by 8q24 amplification, which is closely related to the activation of multiple MYC pathways." (PMID 36008934, 2022). "This work is to discover potent ATAD2 inhibitors and elucidate the underlying mechanisms in breast cancer." (PMID 32174193, 2020). "Studies have revealed that ATAD2 is highly expressed and associated with proliferation and metastasis in several types of tumors, such as breast cancer, lung cancer, and hepatocellular carcinoma." (PMID 29515109, 2018). "High ATAD2 expression has been linked to aggressive disease in breast cancer and endometrial cancer but little is known regarding the variation in ATAD2 mRNA expression related to different stages of disease development for endometrial cancer." (PMID 26308378, 2015). "This is in line with findings from breast cancer, where high ATAD2 detected by IHC is associated with aggressive disease." (PMID 26308378, 2015). "Moreover, the elevated expression of ATAD2 is further associated with tamoxifen-resistant phenotypes in breast cancer." (PMID 36139505, 2022). "To further investigate the effect of ATAD2 on breast cancer cell behaviors associated with malignant progression, we examined whether it affects cancer cell migration and invasion." (PMID 36139505, 2022). "ATAD2 overexpression is associated with poor survival and disease recurrence in multiple cancers, and its elevated expression is associated with chemoresistant phenotypes of the colon, gastric, and breast cancers." (PMID 36139505, 2022). "Our findings indicate that miR-302 plays a prominent role in inhibiting the cancer cell behavior associated with tumor progression by targeting ATAD2, and could thus be a valuable target for breast cancer therapy." (PMID 36139505, 2022). "In concordance with findings from breast cancer we find that ATAD2 overexpression correlate strongly with expression of genes associated with increased proliferation, suggesting that ATAD2 either act as an upstream mediator of their expression or as a collaborator of their function." (PMID 26308378, 2015). "However, the molecular mechanisms underlying the regulation of ATAD2 expression in breast cancer remain unclear." (PMID 36139505, 2022). "Encouragingly, a recent study found that AM879, an inhibitor of ATAD2, blocks the PI3K-AKT-mTOR pathway through ATAD2 inhibition, thereby facilitating breast cancer cell apoptosis and autophagy-associated cell death." (PMID 36632213, 2023). "The current study showed that miR-302 downregulates ATAD2 expression to inhibit breast cancer cell proliferation, migration, and invasion in vitro and tumor growth in vivo." (PMID 36139505, 2022). "To investigate the possible role of ATAD2 in the malignant phenotypes of breast cancer cells, we established ATAD2-depleted SKBR3 and T47D cell lines via transfection with short hairpin RNAs (shRNAs) targeting ATAD2." (PMID 36139505, 2022). "In breast cancer, ATAD2 has been identified as an ERα coregulatory factor that plays a critical role in ER-mediated activation." (PMID 36139505, 2022). "Our results showed that ATAD2 expression was upregulated in human breast cancer tissues and cell lines, while ATAD2 knockdown inhibited the proliferation, migration, and invasion of breast cancer cells." (PMID 36139505, 2022). "A combination of structure-based virtual screening and biochemical analysis led to the finding of a new inhibitor (AM879) for ATAD2 bromodomain, which is able to trigger apoptosis and autophagy in breast cancer cells via PI3K-AKT-mTOR signaling." (PMID 36008934, 2022). "In the current study, we describe novel molecular mechanisms that define a new role of ATAD2 in breast cancer progression." (PMID 36139505, 2022). "ATAD2 is overexpressed in various human cancers, including colorectal, gastric, lung, and breast cancers." (PMID 36139505, 2022).
breast carcinoma (continued). "The ATPase family AAA domain-containing protein 2 (ATAD2) contains an ATPase domain and a bromodomain, and is abnormally expressed in various human cancers, including breast cancer." (PMID 36139505, 2022). "Our results show that ATAD2 expression is upregulated in human breast cancer tissues and cell lines, while ATAD2 knockdown inhibits the proliferation, migration, and invasion of breast cancer cells." (PMID 36139505, 2022). "ATAD2 first attracted attention as a co-activator of estrogen and androgen receptors in breast cancer, and subsequent research also found a high expression of ATAD2 in other human cancers." (PMID 36008934, 2022). "Encouragingly, in cancer settings, ATAD2 was found upregulation in breast cancer for the first time and acted as a co-regulator in mediating expression of cell cycle regulators." (PMID 33757572, 2021). "Collectively, these findings shed light on a novel and promising lead compound for the development of ATAD2 inhibitors and characterised the biological function for breast cancer therapy." (PMID 32174193, 2020). "Upregulaton of ATAD2 in cancer tissues compared to paired normal tissues has been reported previously in multiple cancers, such as renal cell carcinoma 22, breast cancer 23 and prostate cancer." (PMID 32669963, 2020). "This study demonstrates the development of potent ATAD2 inhibitors with novel scaffolds for breast cancer therapy." (PMID 32174193, 2020). "Accumulating studies have demonstrated that ATAD2 is highly expressed in numerous cancers, including lung adenocarcinoma, colorectal, gastric and breast cancer." (PMID 32174193, 2020). "To further investigate the role of JQ1 in AR expressing breast cancer cells, we assessed protein-protein interactions among ATAD2, AR, as well as JQ1 targets including BRD2, and BRD4." (PMID 31527644, 2019). "The ATPase family AAA domain-containing protein 2, ATAD2, is highly expressed in several types of tumors, such as breast cancer, lung cancer, and large B-cell lymphoma." (PMID 28415780, 2017). "The human homolog of Yta7 is ATAD2, which contains a bromodomain and an ATPase domain and its expression levels correlate with the clinical outcome of breast cancer patients." (PMID 29212286, 2017). "The overexpression of ATAD2 has been reported in multiple solid tumors in humans, such as breast cancer, cervical cancer, glioma, hepatocellular carcinoma, ovarian carcinomas and gastric cancer." (PMID 28449718, 2017). "The expression of ATAD2, the human homolog of Yta7 correlates with clinical outcome of breast cancer patients." (PMID 29212286, 2017). "We confirmed the proliferation inhibition upon ATAD2 depletion in other breast cancer cell lines including T47D, BT-549 and MDA-MB-231." (PMID 27612420, 2016). "ATAD2 through different mechanisms broadly participated in various tumor types, such as prostate cancer, lung cancer, breast cancer, and ovarian cancer." (PMID 26697062, 2015). "Further studies demonstrated that ATAD2 is overexpressed in several types of human cancers, including breast cancer, prostate cancer and lung cancer." (PMID 26308378, 2015). "Studies have revealed that ATAD2 is highly expressed in several types of tumors such as breast cancer, lung cancer, and gastric cancer." (PMID 26697062, 2015). "We here apply an antibody previously shown to specifically detect ATAD2 expression in breast cancer to explore the potential for clinical implementation of ATAD2 as a biomarker for aggressive disease in endometrial cancer." (PMID 26308378, 2015). "Studies have revealed that ATAD2 is highly expressed in several types of tumors such as breast cancer, lung cancer, and large B-cell lymphoma." (PMID 24552534, 2014). "Similar results were also observed in other human malignancies, such as esophageal, gastric, colon, and breast cancers, in which the overexpression of the ATAD2 gene was often observed in more aggressive tumor subgroups and provided diagnostic value." (PMID 24552534, 2014).
breast carcinoma (continued). "We also found that ATAD2 copy-number and E2F expression independently predicted ATAD2 expression in breast cancer, ovarian cancer and glioblastoma." (PMID 23393560, 2013). "Knockdown of ATAD2 and MYC in seven endometrial and 21 breast cancer cell lines demonstrated that cell lines that were dependent on MYC also depended upon ATAD2." (PMID 23393560, 2013). "We also find that endometrial and breast cancer cell lines that are dependent upon MYC expression also depend upon expression of ATAD2." (PMID 23393560, 2013). "When we tested a larger panel of 21 breast cancer lines, however, we confirmed the strong correlation between decrease in viability after knockdown of ATAD2 or MYC (R2 = 0.61, p<0.001)." (PMID 23393560, 2013). "Moreover, ATAD2 is a critical intermediary of DNA damage response and repair in breast cancer cells, through mediating Chk1, Chk2, and BRCA1, which have an essential role in the dissolution of DNA damage foci and homologous recombination in BC." (PMID 36008934, 2022). "Together, these findings show that ATAD2 expression increases in human breast cancer tissues and cell lines, suggesting that ATAD2 may be involved in tumorigenesis." (PMID 36139505, 2022). "To verify the expression of ATAD2 protein in breast cancer, we performed immunohistochemistry." (PMID 36139505, 2022). "ATAD2 also promotes breast cancer proliferation and survival through steroid hormone signaling." (PMID 36008934, 2022). "A study on breast cancer established that ATAD2 could be recruited to the KIF4A promoter region by estrogen receptors alpha (ERα) and other transcription factors to increase the transcription of KIF4A." (PMID 36046597, 2022). "Studies have found that ATAD2 plays an important role in the progression of various tumors, including breast cancer, lung cancer, prostate cancer, hepatocellular carcinoma, and cervical cancer, and is involved in regulating tumor cell growth, migration, differentiation, cell cycle, and apoptosis." (PMID 36046597, 2022). "ATAD2 expression levels are correlated with a poor prognosis in patients with breast cancer." (PMID 36139505, 2022). "The current study aimed to investigate the expression and function of ATAD2 in breast cancer." (PMID 36139505, 2022). "This study aimed to investigate the expression and function of ATAD2 in breast cancer." (PMID 36139505, 2022). "We found that ATAD2 was highly expressed in human breast cancer tissues and cell lines." (PMID 36139505, 2022). "ATAD2 also takes part in the PI3K-AKT-mTOR oncogenic signaling pathway in breast cancer." (PMID 36008934, 2022). "The results may provide meaningful clues for the further development of ATAD2 inhibitors with novel scaffolds to treat breast cancer." (PMID 32174193, 2020). "Specifically, ATAD2 up-regulation was observed in 760 cancer samples of 14 different origins, compared to 112 normal somatic tissues, and this up-regulation was correlated with poor prognosis in lung cancer, breast cancer, osteosarcoma, and HCC." (PMID 26497681, 2015). "ESR1, which was less strongly associated with ATAD2 expression, was significant in the adjusted model only in endometrial cancer (p = 0.016) and glioblastoma (p<0.001), not in ovarian or breast cancer." (PMID 23393560, 2013). "Similarly, the histone demethylase KDM2A (induced) acts as E3 ligase to regulate RNAPII ubiquitination and ER-mediated gene repression, whereas ATAD2 (repressed) regulates p300-mediated histone hyperacetylation to activate ER target genes involved breast cancer biology." (PMID 38625038, 2024). "ATAD2 is strongly induced by E2, cooperates with E2F to positively regulate the proto-oncogene ACTR, and directly interacts with ERα and ACTR to stimulate the ERα target gene presentation, causing cell cycle progression (G1/S transition) and proliferation of breast cancer cells induced by estrogen." (PMID 36008934, 2022).
breast carcinoma (continued). "Additionally, ATAD2 functions as a co-activator of the estrogen receptor and the androgen receptor, implicating it as an oncogenic protein in hormone-related cancers such as breast cancer and prostate cancer." (PMID 26497681, 2015). "Analysis of microarray data using the KM Plotter tool showed that overexpression of ATAD2, E2F1, and FOXM1, each conferred significantly poorer recurrence-free survival in breast cancer patients." (PMID 39335162, 2024). "In breast cancer datasets, we found significant upregulation of both centrosome clustering proteins KIFC1, AURKB, BIRC5, and CDCA8 and the oncogenes FOXM1, ATAD2, and E2F1 in tumor samples compared to normal samples." (PMID 39335162, 2024). "ATAD2 depletion via RNA interference inhibited the proliferation, migration, and invasive ability of the SKBR3 and T47D breast cancer cell lines." (PMID 36139505, 2022). "In breast cancer, E2F1 protein regulates ATAD2 gene expression and B-MYB has been reported to have a role in ATAD2 driven cell proliferation." (PMID 26308378, 2015). "RT-PCR analyses showed that ATAD2 mRNA was expressed in seven breast cancer cell lines, but not in the human normal breast cell line MCF-10A." (PMID 36139505, 2022). "Intense staining for ATAD2 was observed frequently in breast cancer tissue specimens, while negative or very weak staining was observed in normal tissue specimens." (PMID 36139505, 2022). "ATAD2 colocalized with newly incorporated DNA (EdU) and the essential DNA replication protein PCNA at replication foci in MCF7 cells and in several other breast cancer cell lines (T47D, BT-549 and MDA-MB-231) independent of their hormone dependency." (PMID 27612420, 2016). "Kinesins have important roles in cell division and signaling, and ATAD2 has been shown to regulate expression of key kinesin members, both in the presence and absence of estrogen in breast cancer cell lines." (PMID 26308378, 2015). "As already shown in breast cancer, we also find several members of the Kinesin protein family (KIF11, KIF15, KIF23, KIF2C and KIFC1) to be upregulated in patients with high expression of ATAD2." (PMID 26308378, 2015). "Furthermore, in The Cancer Genome Atlas (TCGA) data, ATAD2 mRNA expression was upregulated in the human breast cancer tissues compared to the non-tumor samples." (PMID 36139505, 2022). "Additionally, ATAD2 could positively mediate the expression of pro-survival genes, including SGK, VEGF, IRS2 and Akt, which contribute to promoting breast cancer progression." (PMID 32174193, 2020). "Moreover, low levels of ATAD2 expression were reported after a comparison of metastatic and nonmetastatic breast cancer patients and controls, which differed from plausibly consistent viewpoints that ATAD2 was highly expressed in many cancers." (PMID 32462022, 2020). "Several BrD members, namely BRPF1, SMARCA4, BRD7, BRD9, BAZ1B, ATAD2 and BRD4 are significantly upregulated in basal breast cancer subtype (when compared to less aggressive luminal A and normal‐like subtype), which strongly mimics the results obtained for the mRNA‐SI." (PMID 35049055, 2022).
hepatocellular carcinoma (19 papers, 2013 to 2026). A malignant tumor that arises from hepatocytes. "Similarly, inhibition of NUSAP1 or ATAD2 caused apoptosis in human colorectal cancer or hepatocellular carcinoma, respectively." (PMID 30560474, 2019). "In hepatocellular carcinoma, ATAD2 modulates the expression of kinesin family member 15, which interacts with phosphoglycerate dehydrogenase to prevent its proteasomal degradation." (PMID 41158756, 2026). "Of note, abnormal regulation of the cell cycle is also a major feature of tumors, and knockdown of the ATAD2 gene leads to decreased expression of cyclin C and cyclin D1 in hepatocellular carcinoma, which is beneficial for cancer treatment." (PMID 36632213, 2023). "ATAD2 is overexpressed in hepatocellular carcinoma, and its overexpression level positively correlates with aggressive phenotype and disease progression." (PMID 36008934, 2022). "We aim to understand the clinical and biological significance of ATAD2 over-expression in hepatocellular carcinoma (HCC), as a means to validate it as a therapeutic target in HCC." (PMID 26497681, 2015). "Depletion of ATAD2 could reduce the mRNA expression of Myc and the key genes in hepatocellular carcinoma." (PMID 36428626, 2022). "ATAD2 is overexpressed in various human malignancies, including HCC; it is a potential proliferation marker for liver regeneration and is a poor prognostic marker for hepatocellular carcinoma after curative resection." (PMID 36557005, 2022). "In hepatocellular carcinoma (HCC), ATAD2 suppression lowers Myc mRNA expression." (PMID 41154392, 2025). "MiR-372 binds to the ATAD2 3′-UTR and downregulates its expression to inhibit the proliferation of ovarian and hepatocellular carcinoma cells." (PMID 36139505, 2022). "However, no studies have been conducted on the molecular biological function of the ATAD2 gene in hepatocellular carcinoma (HCC)." (PMID 24552534, 2014). "ATPase family AAA domain-containing protein 2 (ATAD2), a chromatin regulator and an oncogenic transcription cofactor, is frequently overexpressed in many cancers, particularly in hepatocellular carcinoma (HCC)." (PMID 32462022, 2020).